NPHS2 (NPHS2 stomatin family member, podocin)
Description:
Plays a role in the regulation of glomerular permeability, acting probably as a linker between the plasma membrane and the cytoskeleton.
Synonyms: SRN1; PDCN
Tractability: Antibody: UniProt places it where antibodies can reach, with high confidence; its Gene Ontology location is reachable by antibodies, with high confidence.
Gene: Protein-coding gene on chromosome 1 (179,550,494 to 179,575,952, reverse strand). Ensembl gene ENSG00000116218.
Subcellular location: Cell membrane (Isoform 1); Endoplasmic reticulum (Isoform 2)
Pathways (Reactome):
Cell-Cell communication: Nephrin family interactions
Gene Ontology:
Molecular function: protein binding
Biological process: actin cytoskeleton organization; metanephric podocyte development; glomerular filtration
Cellular component: cell-cell junction; cytoplasmic side of plasma membrane; endoplasmic reticulum; extracellular exosome; membrane raft; protein-containing complex; slit diaphragm; plasma membrane; cell periphery; membrane
Genetic constraint (gnomAD): Loss-of-function variants: 33 observed, 33.46 expected, observed/expected ratio (o/e) 0.99, 90% interval 0.75 to 1.32. The upper end of that interval is the gene's LOEUF score, 1.32, which puts it in group 5 of 6, group 1 being the genes least tolerant of losing a copy. Missense variants: 429 observed, 431.57 expected, observed/expected ratio (o/e) 0.99, 90% interval 0.92 to 1.08. Synonymous variants: 189 observed, 163.73 expected, observed/expected ratio (o/e) 1.15, 90% interval 1.02 to 1.3.
Homologues: Orthologues: chimpanzee NPHS2 (99% identical), macaque NPHS2 (98% identical), pig NPHS2 (87% identical), rabbit NPHS2 (87% identical), dog NPHS2 (87% identical), mouse Nphs2 (86% identical), rat Nphs2 (85% identical), guinea pig NPHS2 (84% identical), tropical clawed frog nphs2 (54% identical), zebrafish nphs2 (45% identical). Paralogues in human: STOM (35% identical), STOML3 (33% identical), STOML1 (21% identical), STOML2 (19% identical).
Diseases named in the same sentence as NPHS2 in open-access papers:
NPHS2 is named in the same sentence as 56 diseases in open-access papers, as found by Europe PMC text mining. Sharing a sentence is not in itself a finding about the gene and the disease. The quoted sentences say what the papers report.
nephrotic syndrome (39 papers, 2007 to 2025). A collection of symptoms that include severe edema, proteinuria, and hypoalbuminemia; it is indicative of renal dysfunction. "The NPHS2 c.868G>A (p.Val290Met) variant is recurrent in Czech patients with steroid-resistant nephrotic syndrome (SRNS); it accounts for approximately 75% of all NPHS2 pathogenic alleles." (PMID 39273284, 2024). "Kashubians, a Slavic ethnic isolate living in the North-West of modern Poland, are characterized by the persistence of a “regional” founder variant NPHS2 c.1032delT (p.Phe344Leufs*5) causing steroid-resistant nephrotic syndrome." (PMID 39273284, 2024). "The unusually late onset of NPHS2 Val290Met-associated steroid-resistant nephrotic syndrome probably leads to the underdiagnosis of this condition." (PMID 39273284, 2024). "More recently, renal organoids were cultured from a patient with NPHS2 mutations and were thus used to model congenital nephrotic syndrome." (PMID 36831216, 2023). "Both developmental and inducible activation of transgenic PAR-1 (NPHS2 Cre PAR-1Active+/−) caused early severe nephrotic syndrome, FSGS, kidney failure and, in the developmental model, premature death." (PMID 36940798, 2023). "The NPHS2 gene, encoding the slit diaphragm protein podocin, accounts for genetic and sporadic forms of nephrotic syndrome (NS)." (PMID 31368174, 2019). "Nephrotic syndrome caused by NPHS2 mutations has a variable disease course and can cause congenital/infantile nephrotic syndrome or manifest later in childhood or as adult-onset SRNS." (PMID 29594119, 2018). "The key words “NPHS2”, “NPHS2 mutations”, “podocin” and “steroid resistant nephrotic syndrome genetics” were used in PubMed databank." (PMID 28785586, 2017). "After molecular analysis of the genes more frequently reported as mutated in 27 steroid-resistant nephrotic syndrome patients, we identified NPHS2 mutations confirming the hereditary character of the kidney disease in only 14.8 % of patients." (PMID 26420286, 2015). "NPHS2 G>A has a statiscal connection with nephrotic syndrome, indicating that the G allele is the codominant allele in a healthy individual while the A allele increases the risk of nephrotic syndrome." (PMID 37014572, 2023). "Here, we used kidney organoids to model the congenital nephrotic syndrome caused by NPHS2 mutation." (PMID 35417019, 2022). "NPHS2 is independently called podocin, which its mutations that cause severe nephrotic syndrome." (PMID 35130988, 2022). "The NPHS2 variant has been found with a frequency of 0,03 according to the ExAc database; however it has been previously reported as likely pathogenic (rs61747728) and associated with nephrotic syndrome." (PMID 30808327, 2019). "Mutations in the NPHS2 gene, encoding podocin, cause hereditary nephrotic syndrome." (PMID 29049388, 2017). "Furthermore, podocin (Nphs2) is a critical protein component of podocyte filtration slits, and its deficiency or mutation can cause focal segmental glomerulosclerosis leading to nephrotic syndrome, with massive leakage of albumin into urine." (PMID 32400101, 2020).
nephrotic syndrome (continued). "Genetic variants in NPHS1, NPHS2, and CD2AP demonstrate the strongest causal link to human nephrotic syndromes, reflecting their indispensable structural and signaling functions." (PMID 41368354, 2025). "Similar attention is warranted for NPHS2 (HGNC:13394), considering its association with nephrotic syndrome." (PMID 38790019, 2024). "The contents of UP, SCR, and BUN were significantly increased, the glomerulus was seriously damaged, and the expression of Nephrosis2 (NPHS2) was significantly decreased in the ADR-induced nephrotic syndrome rat model compared to that of the control group." (PMID 36707848, 2023). "Mutations in the NPHS1, NPHS2, LAMB2, and the WT1 genes are responsible for causing nephrotic syndrome (NS) in two third of the early onset cases." (PMID 30013592, 2018). "Other genes up-regulated in the early testis show an overlap with mesonephric development and factors involved in nephrotic syndrome (e.g.,NPHS2,WT1)." (PMID 28459107, 2017). "The best characterized inherited nephrotic syndromes are congenital nephrotic syndrome of the Finnish type (CNF) and Steroid Resistant Nephrotic Syndrome (SRNS), due to mutations in NPHS1 and NPHS2 genes, respectively." (PMID 21904677, 2011). "In addition, nephrin gene (NPHS1, NPHS2) mutations are known to be causative genes of FSGS, a representative disease of nephrotic syndrome." (PMID 40005987, 2025). "Similarly, NPHS2 and PLCE1 mutations are linked to steroid-resistant nephrotic syndrome, with clear genotype-phenotype correlations." (PMID 41368354, 2025). "Notably, within this population, genes associated with nephrotic syndromes include MYOE1, NPHS1, NPHS2, and PLCE." (PMID 39519211, 2024). "The commonest genes associated with nephrotic syndrome differ at birth (NPHS1, NPHS2, WT1, LAMB2, PAX2, PLCE1), in childhood or adolescence (NPHS1, NPHS2, WT1, LAMB2, SMARCAL1, NUP107, TRPC6, PLCE1) and in adults (COL4A3-COL4A5, GLA, ACTN4, CD2AP, INF2, TRPC6)." (PMID 37578539, 2024). "Especially in individuals presenting with FSGS or nephrotic syndrome before or at the age of 18 years old, the most common genes in which a mutation was found continues to be limited to only a few genes, including NPHS1 and NPHS2." (PMID 31216994, 2019). "Other types of nephrotic syndrome (NS), including familial and sporadic steroid resistant nephrotic syndrome (SRNS) (28–40% and 6–19%, respectively), adult-onset FSGS, and non-diabetic ESKD in African Americans have also found to exhibit NPHS2 mutations." (PMID 30255020, 2018). "Moreover, nephrin deficiency was detected in other forms of nephrotic syndrome, and an overlap in the genes encoding nephrin/podocin (NPHS1/NPHS2) mutation spectrum (a triallelic hit) has recently been documented in patients with congenital FSGS." (PMID 17347836, 2007). "However, it should be remembered that not all familial cases of steroid-resistant nephrotic syndrome are linked to NPHS2 gene, indicating that other genes remain to be identified." (PMID 21904677, 2011). "For example, mutations of podocyte-associated genes account for approximately 30% of pediatric cases of steroid-resistant nephrotic syndrome with one of the four genes (NPHS1, NPHS2, WT1, and LAMB2) identified in 66% of nephrotic syndrome manifesting within the first year of life." (PMID 31049720, 2020). "When compared with monogenic mutations sharing a common nephrotic syndrome phenotype, the RCAD146 classifier also identified subjects carrying mutations in NPHS1, NPHS2, WT1 (NPHS4), and ADCK4 (NPHS9) as non-RCAD." (PMID 30778115, 2019).
focal segmental glomerulosclerosis (13 papers, 2008 to 2024). A renal disorder characterized by sclerotic lesions in the glomeruli. "Nevertheless, there is wide overlap between different forms and cases of uncommon associations, such as the presence of diffuse mesangial sclerosis in patients with NPHS2 mutations or focal glomerulosclerosis in patients with variants in the PLCE1 gene." (PMID 19066979, 2010). "A podocyte-specific Coq6 KO mouse model (Nphs2-cre;Coq6loxP/loxP) was generated and described to recapitulate aspects of the pathology of focal segmental glomerulosclerosis (FSGS) observed in patients with COQ6 mutations." (PMID 38722242, 2024). "Positional cloning identified NPHS2, encoding podocin, as a causative gene in autosomal recessive SRNS, including focal segmental glomerulosclerosis (FSGS)." (PMID 28529802, 2017).
congenital nephrotic syndrome (10 papers, 2010 to 2024). "Second, we detected three congenital nephrotic syndrome (CNS) gene variants, NPHS2 (five cases), NPHS1 (two cases), and WT1 (one case) in eight patients with a mean age of 52 months." (PMID 39625990, 2024). "Most of the genes commonly associated with congenital nephrotic syndrome have reported ocular manifestations (NPHS1, NPHS2, WT1, LAMB2, PAX2, PLCE1)." (PMID 37578539, 2024). "The identification of mutations in congenital nephrotic syndrome in important podocyte genes (NPHS1 and NPHS2) also defines iNS as a podocytopathy." (PMID 35417019, 2022). "Compound heterozygous mutations p.Arg138Gln (exon 3) and p.Asp160Tyr (exon 4) in the podocin (NPHS2) gene were identified in a patient with congenital nephrotic syndrome." (PMID 35417019, 2022). "Digenic inheritance has also already been reported to have a prognostic role in other kidney diseases, such as congenital nephrotic syndrome (mutations in NPHS1 and NPHS2), autosomal dominant polycystic kidney disease (mutations in PKD1 and PKD2) and Bartter's syndrome." (PMID 33330536, 2020). "Currently, three genes are associated with congenital nephrotic syndrome: NPHS1, NPHS2, and WT1." (PMID 21904677, 2011).
steroid-resistant nephrotic syndrome (9 papers, 2013 to 2025). Nephrotic syndrome, occurring in the pediatric population, in which proteinuria does not normalize with administration of steroids; this condition is unresponsive to a minimum of four weeks administration of oral corticosteroids. "NPHS2 mutations are associated with autosomal recessive steroid-resistant nephrotic syndrome (SRNS)." (PMID 41368354, 2025). "In humans, it was reported that autosomal-recessive steroid-resistant nephrotic syndrome is associated with NPHS2 mutations, and podocin mutations result in changes in the distribution of nephrin and other proteins in podocytes." (PMID 37510393, 2023). "The most common genetic causes of steroid-resistant nephrotic syndrome (SRNS) are mutations in the NPHS2 gene, which encodes the cholesterol-binding, lipid-raft associated protein podocin." (PMID 38114895, 2023). "FSGS is the typical histopathological lesion found in renal biopsies of patients with steroid resistant nephrotic syndrome (SRNS) due to NPHS2 mutations." (PMID 29049388, 2017). "NPHS1 and NPHS2, the responsible genes for Finnish-type congenital nephrotic syndrome and autosomal recessive steroid-resistant nephrotic syndrome, respectively, encode nephrin and podocin, both of which are expressed in podocytes." (PMID 25184792, 2014). "Steroid resistant nephrotic syndrome is a severe hereditary disease often caused by mutations in the NPHS2 gene." (PMID 23648087, 2013). "The first gene, NPHS2, is located on chromosome 1q25-q31 and was initially mapped through linkage analysis in families affected by autosomal recessive steroid-resistant nephrotic syndrome." (PMID 37510393, 2023).
Nephropathy (8 papers, 2017 to 2024). A nonspecific term referring to disease or damage of the kidneys. "He carried a pathogenic mutation, NPHS2 p.V260E, reported in nephropathy and a new variant p.R838Q in SCN11A, a gene involved in familial episodic pain syndrome." (PMID 30533233, 2018). "Median ESKD-free survival time was 8.7 (95% CI 8.0–9.4) years for SMARCAL1 vs. 13.0 (95%CI 11.8–14.1) years for NPHS2 nephropathy (p = 0.013)." (PMID 28796785, 2017). "To begin testing for functional links between ROCK2 expression and ADR-induced kidney damage, we crossed Rock2-flox mice with mice expressing Cre recombinase under the control of the Nphs2/Podocin promoter to generate mice with podocyte-specific disruption of ROCK2." (PMID 38565675, 2024).
chronic kidney disease (6 papers, 2017 to 2026). Impairment of the renal function secondary to chronic kidney damage persisting for three or more months. "Mutations in the NPHS2 gene disrupt nephrin targeting to lipid raft microdomains, leading to proteinuria and rapid progression to end-stage renal disease." (PMID 36632460, 2023). "It is reported that CTCF can regulate miR-185-5p/NPHS2 axis with a net effect of alleviating renal interstitial fibrosis in chronic kidney disease." (PMID 34424825, 2021). "The most common carrier genes detected were not KSD-associated, including susceptibility to end stage renal disease (APOL1, N = 16), congenital nephrotic syndrome type 2 (NPHS2, N = 6), sickle cell disease (HBB, N = 3), and methylmalonic aciduria (MUT, N = 3)." (PMID 40126616, 2025).
diabetes (5 papers, 2017 to 2024). "Together with the increased expression Nphs2, a marker for podocyte damage, our data thus indicate that Hif1α partial deficiency combined with diabetes accelerates podocyte loss and the inability to sustain the glomerular filtration barrier." (PMID 28774305, 2017). "In our study, the expression of NPHS-2, a marker of active podocyte, was improved in diabetes rats treated with CoQ10-LIP+UTMD." (PMID 29589596, 2018). "Then, we generated mice with podocyte-specific deletion of PVT1 (Nphs2-Cre/Pvt1flox/flox) and confirmed that the deletion of PVT1 suppressed podocyte mitochondrial dysfunction and inflammation in addition to ameliorating diabetes-induced podocyte injury, glomerulopathy, and proteinuria." (PMID 39349450, 2024).
glomerulopathy (5 papers, 2020 to 2025). "We analyzed podocin (NPHS2) gene variants in 50 members of four generations of a family with late-onset presentation of glomerular disease." (PMID 33193607, 2020). "The genes with the highest lifetime risk for monogenic glomerulopathy were COL4A3, followed by COL4A4, CRB2, NPHS1, and NPHS2." (PMID 40677321, 2025). "Taken together, this last group of studies and ours strongly suggest that the NPHS2‐Cre transgene can be safely used in glomerular disease models for podocyte‐specific gene targeting in young C57BL/6J adult mice." (PMID 36082952, 2022). "Given that we are commonly using the NPHS2‐Cre lines to assess the role of proteins of interest in the context of glomerular diseases in 2‐to 4‐month‐old animals, we decided to characterize the phenotype of heterozygous NPHS2‐Cre mice at baseline and in pathological conditions in young adult mice." (PMID 36082952, 2022). "We also wondered whether or not the induction of a glomerulopathy might unmask a more severe disease in NPHS2‐Cre+/− mice despite a similar phenotype at baseline." (PMID 36082952, 2022).
renal failure (5 papers, 2008 to 2023). "For example, mutations affecting NPHS1 (encoding the slit diaphragm protein, nephrin) or NPHS2 (encoding the slit diaphragm-associated protein, podocin), result in renal failure and death within a few days after birth." (PMID 23236390, 2012). "Mutations in the podocin gene (NPHS2) result in nephritic syndrome, in which protein appears in the urine; the end stage of this condition is renal failure." (PMID 18267007, 2008). "NPHS2 Cre PAR-1Active+/− mice were also in renal failure as evidenced by their significantly higher levels of serum creatinine and urea compared with littermate controls (respectively)." (PMID 36940798, 2023). "The NPHS2 Cre PAR-1Active+/− mice died of renal failure around 40 days of age." (PMID 36940798, 2023). "A recent study of a podocyte-specific Lmx1b knockout (using a Cre-Lox system based on the NPHS2 promoter) showed later development of proteinuria and greater expression of type IV collagen chains and podocin, although the animals still died of kidney failure within 14 days." (PMID 18535845, 2009).
diabetic nephropathy (3 papers, 2019 to 2025). "Conversely, no CD9 expression was found in PECs in mouse model of diabetic nephropathy, even in a model prone to podocyte injury (i.e. Nphs2.cre Atg5lox/lox)." (PMID 31341160, 2019).
end stage renal disease (3 papers, 2013 to 2025). "The NPHS2 gene—the product being podocin—is mutated in certain patients with autosomal recessive steroid resistant nephrotic syndrome, with disease manifesting early in childhood and progression to end-stage renal failure." (PMID 24327929, 2013).
glomerulosclerosis (3 papers, 2019 to 2022). A hardening of the kidney glomerulus caused by scarring of the blood vessels. "Periodic acid Schiff (PAS) staining revealed a marked increase in mesangial expansion and glomerulosclerosis in Ang II-infused Sirt6flox/flox/Nphs2-Cre+ mice compared with Ang II-infused Sirt6flox/flox/Nphs2-Cre- controls mice." (PMID 32642006, 2020). "This glomerulosclerosis may be due to the NPHS2 polymorphism, as proteinuria was much lower in all other p.G624D-affected family members without the NPHS2 polymorphism (e.g., the sister (II-4) at the same age)." (PMID 30691124, 2019).